CAPZB (capping actin protein of muscle Z-line subunit beta)
Description:
F-actin-capping proteins bind in a Ca(2+)-independent manner to the fast growing ends of actin filaments (barbed end) thereby blocking the exchange of subunits at these ends. Unlike other capping proteins (such as gelsolin and severin), these proteins do not sever actin filaments. Plays a role in the regulation of cell morphology and cytoskeletal organization. Forms, with CAPZB, the barbed end of the fast growing ends of actin filaments in the dynactin complex and stabilizes dynactin structure. The dynactin multiprotein complex activates the molecular motor dynein for ultra-processive transport along microtubules (By similarity).
Synonyms: CAPB; CAPPB; CAPZ
Tractability: Small molecule: a structure with a bound ligand is known. PROTAC: ubiquitination databases record sites on it; its protein half-life has been measured.
Gene: Protein-coding gene on chromosome 1 (19,338,775 to 19,485,600, reverse strand). Ensembl gene ENSG00000077549.
Subcellular location: Cytoplasm, cytoskeleton; Cytoplasm, myofibril, sarcomere
Subcellular location (Human Protein Atlas): Cytosol; Nucleoplasm; Vesicles
Pathways (Reactome):
Signal Transduction: RHOD GTPase cycle; RHOF GTPase cycle
Vesicle-mediated transport: COPI-independent Golgi-to-ER retrograde traffic; COPI-mediated anterograde transport
Cellular responses to stimuli: HSP90 chaperone cycle for steroid hormone receptors (SHR) in the presence of ligand
Hemostasis: Factors involved in megakaryocyte development and platelet production
Immune System: MHC class II antigen presentation
Sensory Perception: Sensory processing of sound by inner hair cells of the cochlea
Gene Ontology:
Molecular function: actin binding; cadherin binding; protein binding
Biological process: barbed-end actin filament capping; actin cytoskeleton organization
Cellular component: extracellular exosome; F-actin capping protein complex; WASH complex; actin cytoskeleton; cytoskeleton; cytosol; perinuclear theca; brush border; cortical cytoskeleton; cytoplasm; hippocampal mossy fiber to CA3 synapse; lamellipodium; membrane; postsynaptic density; sarcomere; Schaffer collateral - CA1 synapse; sperm head-tail coupling apparatus
Genetic constraint (gnomAD): Loss-of-function variants: 1 observed, 21.42 expected, observed/expected ratio (o/e) 0.0467, 90% interval 0.016 to 0.22. The upper end of that interval is the gene's LOEUF score, 0.22, which puts it in group 1 of 6, group 1 being the genes least tolerant of losing a copy. Missense variants: 117 observed, 250.88 expected, observed/expected ratio (o/e) 0.47, 90% interval 0.4 to 0.54. Synonymous variants: 77 observed, 97.12 expected, observed/expected ratio (o/e) 0.79, 90% interval 0.66 to 0.96.
Homologues: Orthologues: chimpanzee CAPZB (99% identical), dog CAPZB (99% identical), mouse Capzb (99% identical), rat Capzb (99% identical), guinea pig CAPZB (99% identical), macaque CAPZB (99% identical), rabbit CAPZB (99% identical), zebrafish capzb (93% identical), pig CAPZB (92% identical), tropical clawed frog capzb (91% identical), Drosophila melanogaster cpb (81% identical), Caenorhabditis elegans cap-2 (66% identical).
Diseases named in the same sentence as CAPZB in open-access papers:
CAPZB is named in the same sentence as 35 diseases in open-access papers, as found by Europe PMC text mining. Sharing a sentence is not in itself a finding about the gene and the disease. The quoted sentences say what the papers report.
breast carcinoma (4 papers, 2021 to 2024). "High expression of F-actin-capping protein subunit β (CAPZB) in the breast cancer cells is linked with α-SMA in regulating breast cancer cell growth and motility." (PMID 38249992, 2024). "We further studied the role of CapZβ in metastasis in our orthotopic cancer mouse model by injecting control or CapZβ-knockout 4T1 mammary carcinoma." (PMID 33564074, 2021). "Interestingly, CapZβ was found to be one of the protein markers for breast cancer grading and staging, and V1 significantly inhibited the metastasis of triple-negative breast cancer (TNBC) cells, e.g., 4T1 and CA1a, in various experimental mouse models." (PMID 33564074, 2021).
hypothyroidism (3 papers, 2012 to 2021). Abnormally low levels of thyroid hormone. "Interestingly, the mineralocorticoid receptor NR3C2 gene has recently been found to be up-regulated in adult-onset hypothyroidism, and PDE8B and CAPZB have been suggestively associated with hypothyroidism by GWAS." (PMID 23408906, 2013).
epithelioid sarcoma (2 papers, 2016 to 2024). An aggressive malignant neoplasm of uncertain differentiation, characterized by the presence of epithelioid cells forming nodular patterns. "A previous proteomics study demonstrated the overexpression of F-actin capping protein subunit beta (CAPZB) in tissue specimens of epithelioid sarcoma (EpiS)." (PMID 26965049, 2016). "CAPZB overexpression has indeed been reported in epithelioid sarcoma tissue specimens, where it increased cell growth and motility, while CAPZA1 could regulate cell growth, invasion, and EMT markers in various human tumors, representing an unfavorable prognostic marker in gastric and lung cancers." (PMID 38607010, 2024).
major depression (2 papers, 2014 to 2018). "A recent proteome study revealed increased levels of F-actin-capping protein subunit beta (CAPZB) in platelets from patients suffering from major depression in comparison to healthy controls." (PMID 30545002, 2018). "The levels of protein disulfide-isomerase A3 (PDIA3) and F-actin-capping protein subunit beta (CAPZB) were higher in patients with major depression than in healthy controls." (PMID 24383611, 2014).
prostate carcinoma (2 papers, 2020 to 2024). A carcinoma that arises from epithelial cells of the prostate gland. "According to data from the Betastasis database, both CAPZA1 and CAPZB mRNA levels positively correlated with PIM1 in primary prostate cancer patient samples." (PMID 32771000, 2020). "When we compared CP expression in different prostate cancer cell lines by Western blotting, we observed slightly lower levels of CAPZA1 in PC-3 cells as compared to the other lines, while CAPZB levels were highest in DU-145 cells." (PMID 32771000, 2020). "Here we show positive correlations between PIM1 and either CAPZA1, CAPZA2 or CAPZB mRNAs in prostate cancer samples with different Gleason grades, but not in the healthy control tissues." (PMID 32771000, 2020).
atherosclerosis (1 paper, 2025). A disease characterized by the build-up of fatty material and calcium deposition in the arterial wall resulting in partial or complete occlusion of the arterial lumen. "Furthermore, CAPZB has been implicated in pathological processes associated with various diseases such as high-grade squamous epithelial lesions and atherosclerosis." (PMID 39951434, 2025).
breast tumor (1 paper, 2022). "It targets capping protein Zβ (CapZβ) to inhibit endosome trafficking, and also significantly suppresses breast tumor metastasis." (PMID 36329484, 2022).
esophageal adenocarcinoma (1 paper, 2021). A malignant tumor with glandular differentiation arising predominantly from Barrett mucosa in the lower third of the esophagus. "The expression levels of CSE1L, RPS15A, SFPQ, and CAPZB in ESCC were significcantly higher than those in normal tissue and esophageal adenocarcinoma (EAC)." (PMID 33842377, 2021).
gastric cancer (1 paper, 2022). A primary or metastatic malignant neoplasm involving the stomach. "CAPZB has oncogenic potential, CAPZA1 inhibits cancer cell migration in gastric carcinoma while CAPZA2 promotes gastric cancer cell migration and invasion." (PMID 36291816, 2022).
glioma (1 paper, 2024). A benign or malignant brain and spinal cord tumor that arises from glial cells (astrocytes, oligodendrocytes, ependymal cells). "Differently, ANXA5 is regarded as a potential early biomarker in hepatocarcinogenesis together with ANXA2 and a predictive biomarker for tumor progression in different cancer types, but it was not so far identified as a specific oncogenic protein in gliomas as well as CAPZB and CAPZA1." (PMID 38607010, 2024).
goiter (1 paper, 2015). Enlargement of the thyroid gland usually caused by lack of iodine in the diet, hyperthyroidism, or thyroid nodules. "Intriguingly, two independent loci associated with goiter risk were found within the CAPZB region on chromosome 1p36: the lead SNP rs10917468 at the locus upstream of CAPZB and the lead SNP rs12045440 located in the first of the 9 introns of CAPZB." (PMID 26273293, 2015). "At the locus 1p36.13, one of the two independent blocks associated with thyroid volume and goiter risk that was reported to be located upstream of CAPZB, of which the lead SNPs Rs10917468 and Rs12138950 are in moderate LD with Rs10917477 (r2 = 0.26 and 0.15, resp)." (PMID 26273293, 2015). "It has been postulated that the CAPZB gene is involved in the risk of goiter." (PMID 26273293, 2015). "Located upstream of CAPZB, rs10917468 represented the lead SNP for goiter, whereas rs12138950 was the lead SNP for thyroid volume." (PMID 26273293, 2015).
hepatoma (1 paper, 2016). "We further confirmed the metastasis-inhibitory effects of Maspin, RhoGDIα and CAPZB in hepatoma cells." (PMID 27391153, 2016). "To query whether HBxΔ31 could repress Maspin, RhoGDIα and CAPZB transcriptions in hepatoma cells, we performed real-time-PCR analysis." (PMID 27391153, 2016).
hypertrophic cardiomyopathy (1 paper, 2024). A condition in which the myocardium is hypertrophied without an obvious cause. "This study revealed the potential relationship between disulfidptosis and hypertrophic cardiomyopathy and put forward a predictive model containing disulfidptosis-associated genes (DRGs) of GYS1, MYH10, PDMIL1, SLC3A2, CAPZB, showing excellent performance by SVM machine learning model." (PMID 39701955, 2024).
lymphoma (1 paper, 2022). A malignant (clonal) proliferation of B- lymphocytes or T- lymphocytes which involves the lymph nodes, bone marrow and/or extranodal sites. "The down-regulated CAPZA1, CAPZB, EFHD2, EZR and PCMT1 proteins are involved in cell–cell adhesion; their reduced levels are compatible with the metastatic behavior of lymphoma cells." (PMID 36291816, 2022).
melanoma (1 paper, 2023). A malignant, usually aggressive tumor composed of atypical, neoplastic melanocytes. "To test the hypothesis of whether Ena/VASP proteins are essential for filopodia formation in CP-deficient cells, we first disrupted the single gene (CapZb) encoding the ß-subunit of CP in B16-F1 mouse melanoma cells using CRISPR/Cas9 technology." (PMID 36980231, 2023).
neuroblastoma (1 paper, 2020). Neuroblastoma (NB) is the most common solid, extracranial childhood tumor. "Furthermore, pull-down of the AMPylated proteins from neuroblastoma cells under FICD E234G OX conditions revealed a general increase in AMPylation including proteins such as CTSB, TPP1, CAPZB, and NSFL1C, which were found AMPylated in COs." (PMID 31980631, 2020).
papillary thyroid carcinoma (1 paper, 2015). "The aim of this study was to investigate the possible influence of different genotypes of the lead single nucleotide polymorphisms (SNPs) rs10917468 and rs12045440 in the CAPZB gene on the thyroid function in papillary thyroid carcinoma (PTC) and benign thyroid neoplasm (BN) patients." (PMID 26273293, 2015).
postpartum hemorrhage (1 paper, 2022). Hemorrhage defined as a blood loss in excess of 500 mL after vaginal delivery or more than 1000 mL after a cesarean delivery. "Eight genes were associated with hemostatic pathways (SELL, CAPZB, SLC16A3, PDPN, TNFRSF10B, SH2B2, NFE2, and TNFRSF10D), which provided novel insights for the prevention and management of postpartum hemorrhage." (PMID 35836580, 2022).
thyroid benign thyroid tumor (1 paper, 2015). "The SNP rs12045440 (1p36) within intron 1 of CAPZB was associated with serum TSH concentrations in Chinese thyroid tumor patients, especially in thyroid benign thyroid tumor cases." (PMID 26273293, 2015).
thyroid tumor (1 paper, 2015). A benign or malignant neoplasm affecting the thyroid gland. "Yet our group confirmed the association between the second genetic locus, of which the lead SNP Rs12045440 is located in intron 1 of CAPZB, and the serum TSH concentrations in Chinese thyroid tumor patients." (PMID 26273293, 2015).
viral infection (1 paper, 2014). "Chicken CAPZB is known to regulate the growth of actin filaments by capping the barbed end, and thus it may also have a role in cytoskeletal reorganization during viral infection." (PMID 24667214, 2014).
ZIKV infection (1 paper, 2024). "We showed that rapamycin markedly inhibited the expression levels of ZIKV envelope (ZIKV-E) protein induced by ZIKV infection in RAB5-FRB/CapZβ-FKBP-expressing A549 cells, but not in control A549 cells." (PMID 38273307, 2024). "Likewise, rapamycin significantly inhibited dsRNA expression induced by ZIKV infection in RAB5-FRB/CapZβ-FKBP-expressing A549 cells, but not in control A549 cells." (PMID 38273307, 2024).
tumor (11 papers, 2011 to 2025). "Other studies have shown that when CAPZB is targeted, its ability to facilitate tumor metastasis is suppressed." (PMID 38732562, 2024). "The effect of CapZβ knockout on tumor growth is likely due to its canonical role in regulating actin polymerization besides endosomal trafficking." (PMID 33564074, 2021). "CapZβ knockout significantly inhibited the metastasis of 4T1 cells, as manifested by the reduced number of tumor nodules per lung in mice implanted with CapZβ-knockout cells, when compared with mice implanted with control cells." (PMID 33564074, 2021). "In all 15 cases, more than 70 ~ 80 % of tumor cells were positive for CAPZB and CAPZB was localized in the cytoplasm." (PMID 26965049, 2016). "These protein profiles help to explain how CAPZB exerts its tumor-accelerating effects in EpiS tissues." (PMID 26965049, 2016). "It is also of interest to identify which biological pathways are involved in promoting the tumor progression induced by CAPZB in cases of EpiS." (PMID 26965049, 2016). "Functional studies further delineated that Maspin, RhoGDIα and CAPZB play important roles during tumor metastasis by influencing cell morphology, adhesion junctions and migration ability of tumor cells." (PMID 27391153, 2016). "This suggests that CapZβ is involved in tumor metastasis in vivo." (PMID 33564074, 2021). "Our previous proteomic study demonstrated the CAPZB expression in the tumor tissues of EpiS." (PMID 26965049, 2016). "Excess dietary iron in tumor tissues was also associated with significant changes (generally, increases; p ≤ 0.05) in proteins involved in modulating cell protein integrity (HSPA5, HSPA9, ITGB1, PSMA4, DPP7, and PEPD), cell mobility and growth (CAPZB), and immunologic factors (FCGBP)." (PMID 38732562, 2024). "Among others, overexpression of serpin H1, F-actin capping protein subunit beta (CAPZB), macrophage capping protein (CAPG), villin 2 (EZR), and cathepsin B (CTSB) are known to promote cell motility and invasion in tumor tissues." (PMID 21305022, 2011). "In summary, we found that CAPZB contributes to the cell growth and motility of EpiS cells, irrespective of the INI1 expression, highlighting a possible role of CAPZB in metastasis and tumor development in cases of EpiS." (PMID 26965049, 2016). "Consequently, silencing of CAPZB definitively suppressed cell proliferation in the setting of EpiS, although, surprisingly, the expression levels of INI1, which possesses a tumor suppressor function, were decreased in the ESX cells." (PMID 26965049, 2016). "CAPZB is involved in tumor progression in cases of EpiS, irrespective of the INI1 expression, and may be a potential therapeutic target." (PMID 26965049, 2016). "While CAPZA1, CAPZA2 and CAPZB, but not CAPZA3 levels correlated well with PIM1 levels in all tumor tissues, similar correlations were also observed for PIM2 and PIM3 in the samples with high Gleason scores." (PMID 32771000, 2020).
cancer (9 papers, 2016 to 2025). A tumor composed of atypical neoplastic, often pleomorphic cells that invade other tissues. "We further identified capping protein Zβ (CapZβ) as a V1 binding protein and showed that it is required for the V1-mediated inhibition of migration and metastasis of cancer cells." (PMID 33564074, 2021). "Nevertheless, these results, in which knockout of RAB5A or CapZβ (two proteins involving in the endocytosis) inhibited cell migration and cancer metastasis, support the role of endosomal trafficking in V1-mediated migration and metastasis inhibition." (PMID 33564074, 2021). "Moreover, CapZβ knockout significantly inhibited the metastasis of 4T1 cells in our orthotopic cancer mouse model." (PMID 33564074, 2021). "However, the associations between the expression levels of capping proteins, including CAPZB, and cancer phenotypes remain unknown." (PMID 26965049, 2016). "The overexpressed proteins, including actinin α1 isoform (ACTN1), annexin A5 (ANXA5), cathepsin D (CTSD), F-actin-capping protein subunit β (CAPZB), inorganic pyrophosphatase (PPA1), and tubulin α1c chain (TUBA1C), are related to cellular structure, growth, or cancer cell invasion." (PMID 38249992, 2024).
infection (3 papers, 2011 to 2025). The state of being infected such as from the introduction of a foreign agent such as serum, vaccine, antigenic substance or organism. "As expected, CAPZB depletion resulted in a striking decrease of the size of the infection foci (CAPZB)." (PMID 21853127, 2011).
CAPZB also shares sentences with these, for which no sentence is quoted: lung carcinoma (2 papers); Adult onset (1); autoimmune disease (1); cataract (1); esophageal cancer (1); hyperthyroidism (1); ovarian carcinoma (1); renal cell cancer (1); Salmonella Infections (1); triple-negative breast carcinoma (1).